NRP2 (neuropilin 2)
Diseases named in the same sentence as NRP2 in open-access papers (continued):
Sharing a sentence is not in itself a finding about the gene and the disease.
anaplastic thyroid carcinoma (1 paper, 2015). "NRP2 expression is significantly increased in all the PTC and follicular thyroid carcinoma samples derived from TRK, RET/PTC3, and N-ras mice and in the anaplastic thyroid carcinoma samples derived from the simian virus 40 large T mice." (PMID 26030152, 2015).
autoimmune disease (1 paper, 2025). A disorder resulting from loss of function or tissue destruction of an organ or multiple organs, arising from humoral or cellular immune responses of the individual to their own tissue constituents. "Although beyond the scope of the current studies, these observations suggest that the combined effects of NRP1 and NRP2 are necessary for Treg function which is critical for long-term transplant survival, the prevention of autoimmune disease, and/or tumor immunity." (PMID 40590224, 2025).
Autoimmunity (1 paper, 2025). The occurrence of an immune reaction against the organism's own cells or tissues. "Notably, in our studies, deletion of NRP2 did not result in any clinical signs of autoimmunity, and phenotyping of KO mice demonstrated normal T cell development." (PMID 40590224, 2025). "Thus, the lack of autoimmunity in KO mice is likely related to the redundancy of NRP2 on Tregs." (PMID 40590224, 2025).
bacterial pneumonia (1 paper, 2024). Acute infection of the lung parenchyma caused by bacteria (e.g., Streptococcus pneumoniae, Haemophilus influenzae, Chlamydia pneumoniae, Mycoplasma pneumoniae, and Legionella pneumophila). "Here, increased Nrp2 expression by pMacs during both bacterial and non-bacterial pneumonia occurs through a MyD88/NF-κβ-dependent signaling pathway." (PMID 38592275, 2024). "In contrast to bacterial pneumonia, Nrp2 may have a different role in viral infections." (PMID 38592275, 2024).
bladder tumors (1 paper, 2019). "Because NRP2 has previously shown to enhance TGFβ signaling, we first aimed to determine the correlation of NRP2 mRNA expression with the expression of other TGFβ regulated genes in bladder tumors." (PMID 32038994, 2019).
carcinoid (1 paper, 2011). "We sought to further elucidate the functional role of NRP-2 and the signaling mechanisms that mediate the function of NRP-2 in GI cancer cells, including gastric and carcinoid cells." (PMID 22028766, 2011). "CNDT2.5 (a human carcinoid cell line) and NCI-N87 expressed the highest levels of NRP-2 and were therefore used for subsequent knockdown studies." (PMID 22028766, 2011).
Cirrhosis (1 paper, 2025). A chronic disorder of the liver in which liver tissue becomes scarred and is partially replaced by regenerative nodules and fibrotic tissue resulting in loss of liver function. "Furthermore, it has been found that the expression of the neuropilin NRP-2 in HCC is associated with tumor histological grade and cirrhosis, and that NRP-2-positive patients with HCC demonstrated shorter disease-free survival and overall survival compared to NRP-2-negative patients." (PMID 40430075, 2025).
colorectal tumors (1 paper, 2022). "The study shows a reduction in the size of hepatic colorectal tumors in mice by a statistically significant margin (p = 0.005) compared to the control group, as a result of the in vivo targeting of NRP-2 by small interfering RNA (siRNA)." (PMID 35052853, 2022).
cystitis (1 paper, 2011). Inflammation of the urinary bladder. "In addition, VEGFR-1 and NRP2 expressions are reduced in bladder biopsies from patients with cystitis." (PMID 22059553, 2011).
demyelinating disease (1 paper, 2023). A broad group of disorders that affect the myelin sheaths that cover the neurons. "Upregulation of C3, Nrp2, Lrp1 was observed in demyelinating disease." (PMID 36817487, 2023).
epilepsy syndrome (1 paper, 2024). A syndrome that has a characteristic cluster of clinical features and/or lectroencephalographic (EEG) findings that reflect underlying epileptic activity. "Our studies using interneuron specific Nrp2 deletion combined with circuit and behavioral analyses support a role for developmental interneuronopathy in comorbidity of ASD-epilepsy syndromes." (PMID 38405865, 2024).
esophageal adenocarcinoma (1 paper, 2024). A malignant tumor with glandular differentiation arising predominantly from Barrett mucosa in the lower third of the esophagus. "We conducted an immunohistochemical evaluation of SEMA3F and NRP2 protein expression in 776 patients with esophageal adenocarcinoma who underwent Ivor-Lewis esophagectomy at the University Hospital of Cologne." (PMID 39232098, 2024). "In this study, we investigated the role of SEMA3F and its receptor, NRP2, in patients diagnosed with esophageal adenocarcinoma." (PMID 39232098, 2024). "Hence, the objective of this study was to elucidate the roles of SEMA3F and its receptor NRP2 in esophageal adenocarcinoma." (PMID 39232098, 2024). "The role of SEMA3F and NRP2 in esophageal adenocarcinoma remains unclear." (PMID 39232098, 2024).
gastric adenocarcinoma (1 paper, 2020). "NRP2 could promote gastric adenocarcinoma lymphatic invasion with VEGF-C stimulation." (PMID 32352015, 2020).
heart failure (1 paper, 2024). Inability of the heart to pump blood at an adequate rate to meet tissue metabolic requirements. "Nrp2 was one of four plasma proteins, along with Beta 2 microglobulin, alpha-1-antichymotrypsin, and complement component C9, that were increased in heart failure patients in relation to disease severity and pulmonary dysfunction." (PMID 38592275, 2024). "Additionally, plasma Nrp2 levels were predictive of heart failure rehospitalizations in patients with preserved ejection fraction, and all-cause mortality in patients with reduced or preserved ejection fraction." (PMID 38592275, 2024).
interstitial lung disease (1 paper, 2024). A diverse group of lung diseases that affect the lung parenchyma. "Efzofitimod is a first-in-class biologic immunomodulator targeting Nrp2 that is in clinical development for the treatment of interstitial lung disease (ILD), a group of immune-mediated disorders that can cause inflammation and progressive fibrosis, or scarring, of the lungs." (PMID 38592275, 2024).
ischemic stroke (1 paper, 2022). A stroke disorder caused by obstruction of blood flow to the brain, due to thrombotic (local blood clot formation) or embolic (due to a blood clot or other material traveling from another site) event. "However, in a recent genome wide association study of neurological instability within the first 24 h after ischemic stroke (n = 5,876) a 2q33.3 loci including both ADAM23 and NRP2 reached genome-wide significance, with indication of ADAM23 driving the association." (PMID 36418382, 2022).
latent infection (1 paper, 2013). "As expected, phoP shows a high transcription rate in hypoxia (NRP1 and NRP2) and during the entire process of latent infection, this observation was in agreement with the increase of the pks genes transcription and the subsequent accumulation of polar precursors." (PMID 23472191, 2013).
lymphangioma (1 paper, 2021). A benign lesion composed of dilated lymphatic channels. "In recurrent lymphangioma, both VEGF-C and Nrp2, but not VEGFR, are upregulated." (PMID 34976885, 2021).
mastocytosis (1 paper, 2025). A clonal myeloproliferative neoplasm characterized by the proliferation and accumulation of neoplastic mast cells in one or multiple organs or organ systems. "Additionally, we observed CD16 (IgG Fc receptor III, FcγIIIb) expression on NRP2-positive mast cells, which has been linked to systemic mastocytosis." (PMID 41159753, 2025).
mesothelioma (1 paper, 2013). A usually malignant and aggressive neoplasm of the mesothelium which is often associated with exposure to asbestos. "It has been shown that the expression of VEGFR-1/Flt-1, VEGFR-2/KDR, Nrp-1 and Nrp-2 remains unchanged during the malignant transformation of MCs (e.g. mesothelioma)." (PMID 23585849, 2013).
multiple sclerosis (1 paper, 2023). A progressive autoimmune disorder affecting the central nervous system resulting in demyelination. "The products of C3 and Lrp1 were also shown to play a role in pathogenesis of multiple sclerosis or EAE and the product of Nrp2 is involved in the remyelinating process in demyelinating lesions." (PMID 36817487, 2023).
myeloid neoplasm (1 paper, 2024). Proliferation of myeloid cells originating from a primitive stem cell. "Interestingly, we observe NCAM1 and NRP2 colocalization in the endosteal niche in sparse endosteal stromal cells in normal BM that increased in myeloid neoplasms associated with fibrosis." (PMID 38792002, 2024). "Thus, other myeloid neoplasms could also respond to NRP2 modulation." (PMID 38792002, 2024).
myeloproliferative neoplasm (1 paper, 2024). A clonal hematopoietic stem cell disorder, characterized by proliferation in the bone marrow of one or more of the myeloid (i.e., granulocytic, erythroid, megakaryocytic, and mast cell) lineages. "Our results suggest that NRP2 is an interesting molecular druggable target in myeloproliferative neoplasm." (PMID 38792002, 2024).
neuroendocrine tumor (1 paper, 2015). "We first aimed to determine the expression profiles of SEMA3F and its preferential receptor NRP-2 in several neuroendocrine tumor cell lines." (PMID 26447612, 2015).
oral squamous cell carcinoma (1 paper, 2023). "In oral squamous cell carcinoma, elevated neuropilin-2 (Nrp2) expression is positively associated with tumor stage, lymphovascular invasion, and lymph node metastasis." (PMID 38201272, 2023).
Osteopenia (1 paper, 2024). Osteopenia is a term to define bone density that is not normal but also not as low as osteoporosis. "This is concordant with earlier in vivo results in Nrp2−/− mice that show osteopenia with thinner bone spicules and a decrease in osteoid-producing osteoblasts in femoral long bones." (PMID 38792002, 2024).
pancreatic neuroendocrine tumor (1 paper, 2024). Pancreatic endocrine tumor, also known as pancreatic neuroendocrine tumor (PNET), describes a group of endocrine tumors originating in the pancreas that are usually indolent and benign, but may have the potential to be malignant. "Administration of Nrp2-blocking antibodies in vivo inhibited tumor vascularity and growth in a mouse model of pancreatic neuroendocrine tumors, repressing F-acting-mediated motility via decreased SSH1-cofilin signaling." (PMID 38592275, 2024). "In addition, vascular expression of Nrp2 promotes angiogenesis and endothelial cell migration in pancreatic neuroendocrine tumors through a VEGF/VEGFR2-independent pathway by activating the SSH1/cofilin/actin axis." (PMID 38592275, 2024).
pneumonia (1 paper, 2024). An acute, acute and chronic, or chronic inflammation focally or diffusely affecting the lung parenchyma, caused by an infection in one or both of the lungs (by bacteria, viruses, fungi, or mycoplasma.). "As defects in innate immunity are associated with pneumonia, the role of Nrp2 as an immunoregulator in the lung has recently been scrutinized." (PMID 38592275, 2024). "In a murine model of E. coli-induced pneumonia, conditional depletion of Nrp2 in pMacs (Nrp2fl/flCD11c-Cre) resulted in pathogenic neutrophil recruitment in the lung associated with severe lung injury, edema, increased pulmonary bacteremia, and reduced survival." (PMID 38592275, 2024). "As an alternate mechanism related to pneumonia, Nrp2 may play an important role in the pMac-mediated clearance of debris and dead cells of the alveoli, known as efferocytosis." (PMID 38592275, 2024).
prostate adenocarcinoma (1 paper, 2021). "It was also reported that NRP2 could act as an independent prognostic factor for prostate adenocarcinoma patients, as its upregulation was correlated with the worse outcome of patients." (PMID 34516335, 2021).
prostate tumor (1 paper, 2021). "Interestingly, depletion of NRP2 in osteoclasts in vivo showed a decrease in the overall prostate tumor burden in the bone." (PMID 33990538, 2021). "We therefore tested whether depletion of NRP2 in the mouse model of bone metastasis would sensitize prostate tumor to docetaxel." (PMID 33990538, 2021).
Sepsis (1 paper, 2025). Sepsis is defined as life-threatening organ dysfunction caused by a dysregulated host response to infection. "Li and Gou found that FOXA1 was able to exacerbate LPS-induced vascular endothelial cell injury in sepsis by inhibiting NRP2 transcription, whereas silencing of FOXA1 reduced inflammatory factor." (PMID 39760528, 2025).
small cell carcinoma (1 paper, 2016). A neuroendocrine carcinoma composed of small malignant cells which are often said to resemble "oat cells" under the microscope. "The frequencies of NRP-1- and NRP-2-positive alveolar macrophages adjacent to small cell carcinomas (n = 3) were also significantly higher than the frequencies of NRP-1- and NRP-2-positive alveolar macrophages in inflamed lung and lung tissue remote to the cancer nest." (PMID 26900851, 2016).
Stroke (1 paper, 2021). Sudden impairment of blood flow to a part of the brain due to occlusion or rupture of an artery to the brain. "However, the lymphocytes in the CLNs involved in the immune damage of stroke also include T and B cells, and many factors, such as neuropilin-2, angiopoietins, BMP9-ALK1, DAMPs, may participate in the activation of lymphatic endothelium after stroke." (PMID 34483842, 2021).
thyroid tumor (1 paper, 2015). A benign or malignant neoplasm affecting the thyroid gland. "Here, we report that the downregulation of NRP2 significantly induces CDH1 expression while inhibits all the mesenchymal markers that we tested, suggesting that this protein might represent a possible new target for preventing thyroid tumor invasion and metastasis." (PMID 26030152, 2015).
ulcers (1 paper, 2022). "The expression levels of PDGFRα and Nrp2 in the mesenchymal cells were higher than the epithelial cells in cardia, cecum, colon, sigmoid, and rectum, especially in the areas with ulcers." (PMID 35027044, 2022). "The expression levels of PDGFRα and Nrp2 in the mesenchymal cells were higher than that in the epithelial cells in cardia, cecum, colon, sigmoid, and rectum, especially in areas with ulcers." (PMID 35027044, 2022). "We found that PDGFRα and Nrp2 all expressed in the epithelial cells and mesenchymal cells, and the expression levels of PDGFRα and Nrp2 in the mesenchymal cells were higher than those in the epithelial cells in cardia, cecum, colon, sigmoid, and rectum, especially in areas with ulcers." (PMID 35027044, 2022).
urothelial carcinoma (1 paper, 2019). A malignant neoplasm derived from the transitional epithelium of the urinary tract (urinary bladder, ureter, urethra, or renal pelvis). "Because EMT-related signaling pathways are involved in the regulation of cancer stem cell (CSC) phenotype and properties in urothelial carcinoma including BCa, we analyzed if the absence of NRP2 has an impact on the CSC-related properties." (PMID 32038994, 2019).
tumor (190 papers, 2007 to 2026). "This study underscores the distinct and context-dependent roles of NRP isoforms, NRP1 and NRP2, in tumor-associated macrophages across different cancer types." (PMID 40134439, 2025). "Inhibition of NRP-2 function through the application of specific monoclonal antibodies has been shown to result in a significant reduction in tumor-associated lymphangiogenesis, as well as a decrease in metastasis to lymph nodes and other distant sites." (PMID 40430075, 2025). "NRP-2 is associated with the mesenchymal phenotype in vitro, and its expression correlates with a higher stage of tumor advancement in vivo, which indicates a lower degree of cell differentiation." (PMID 40430075, 2025). "Owing to the critical role of NRP2 in modulating CAF function, NRP2 blockade is a potential strategy for disrupting the interactions between CAFs, cancer cells, and other tumor-associated stromal cells within the TME." (PMID 38766528, 2024). "Emerging studies have reported the antitumor effects of anti-NRP1 and -NRP2, mediated by tumor-associated macrophages." (PMID 37190154, 2023). "Combined inhibition of IR signaling and autophagy leads to apoptosis of Nrp2-deficient tumor cells, which can provide ideas for the development of new aggressive CRC combination therapy." (PMID 37020597, 2023). "Transcriptome profiling and tumor tissue analysis showed that Nrp2 loss resulted in mesenchymal-to-epithelial transition (MET), which was accompanied with restored polarity and tight junction stabilization." (PMID 35158941, 2022). "Conditional deletion of NRP2 from tumor‐associated macrophages impaired the clearance of apoptotic tumor cells, which was associated with decreased expression of IL‐10 and TGF‐β and enhanced antitumor immune responses." (PMID 34861108, 2022). "The expression level of Nrp2 in tumor-associated lymphatic endothelial cells in colorectal cancer is significantly correlated with tumor lymphatic density." (PMID 36407100, 2022). "Despite being upregulated in tumor-associated lymphatic vessels, Nrp2 is also highly expressed in several cancer types." (PMID 35158941, 2022). "Deletion of NRP2 in tumor‐associated macrophages was reported to result in decreased production of IL‐10 and TGF‐β following exposure to apoptotic cells." (PMID 34861108, 2022). "On the other hand, even in the presence of SEMA3F, the high expression of NRP2 would allow its activity as a potent promoter of tumor-associated lymphangiogenesis." (PMID 35565388, 2022). "In xenografts made from SEMA3F knockdown CRC cells, NRP-2 is significantly activated in tumor-associated LECs, resulting in significantly enhanced tumor lymphangiogenesis." (PMID 35052853, 2022). "Critically however, dual loss of both NRP1 and NRP2 was found to reduce primary tumor growth and primary tumor angiogenesis by a greater extent than when either molecule was targeted individually." (PMID 36970722, 2022). "This study shows that a knockdown of NRP2 has more anti-tumor effects than a knockdown of NRP1, as loss of NRP2 decreases cell proliferation while loss of NRP1 influences cell migration." (PMID 34277411, 2021). "NRP2 expression has been associated both with increased proliferation rate as well as with the capability of tumor cells to escape from programmed cell death in cancer cells." (PMID 34239847, 2021). "In the TCGA cohort, NRP2 and its variants significantly correlated with a higher tumor stage (T3/4 vs. T2), positive lymph node metastasis and recurrence." (PMID 33918816, 2021). "In the TCGA cohort, the NRP2 gene expression was significantly associated with an increased tumor stage as well as locoregional lymph node metastasis." (PMID 33918816, 2021). "Third, neuropilin-2 (NRP2), which is a member of the membrane-associated neuropilin family, is expressed during macrophage differentiation and is induced by tumor cells." (PMID 32509781, 2020).